SLC35D2 (solute carrier family 35 member D2)
Description:
Nucleotide sugar antiporter transporting UDP-N-acetylglucosamine (UDP-GlcNAc) and UDP-glucose (UDP-Glc) from the cytosol into the lumen of the Golgi in exchange of UMP. By supplying UDP-N-acetylglucosamine, a donor substrate to heparan sulfate synthases, probably takes part in the synthesis of these glycoconjugates.
Synonyms: HFRC1; SQV7L; UGTrel8; HFRC
Tractability: Antibody: UniProt predicts a signal peptide or a membrane-spanning region.
Gene: Protein-coding gene on chromosome 9 (96,313,444 to 96,383,711, reverse strand). Ensembl gene ENSG00000130958.
Subcellular location: Golgi apparatus membrane
Subcellular location (Human Protein Atlas): Golgi apparatus
Pathways (Reactome):
Metabolism: Formation of the active cofactor, UDP-glucuronate; HS-GAG biosynthesis; Keratan sulfate biosynthesis
Transport of small molecules: Transport of nucleotide sugars
Gene Ontology:
Molecular function: nucleotide-sugar transmembrane transporter activity; UDP-glucuronate transmembrane transporter activity; UDP-N-acetylgalactosamine transmembrane transporter activity; UDP-N-acetylglucosamine transmembrane transporter activity
Biological process: heparan sulfate proteoglycan biosynthetic process; nucleotide-sugar transmembrane transport; UDP-glucuronate transmembrane transport; UDP-N-acetylgalactosamine transmembrane transport; UDP-N-acetylglucosamine transmembrane transport
Cellular component: Golgi apparatus; Golgi membrane
Genetic constraint (gnomAD): Loss-of-function variants: 9 observed, 5.84 expected, observed/expected ratio (o/e) 1.54, 90% interval 0.88 to 1.94. That is too few expected variants to judge how well the gene tolerates losing a copy. Missense variants: 119 observed, 94.72 expected, observed/expected ratio (o/e) 1.26, 90% interval 1.08 to 1.46. Synonymous variants: 55 observed, 43.62 expected, observed/expected ratio (o/e) 1.26, 90% interval 1.01 to 1.58.
Homologues: Orthologues: chimpanzee SLC35D2 (99% identical), rabbit SLC35D2 (91% identical), pig SLC35D2 (90% identical), mouse Slc35d2 (88% identical), rat Slc35d2 (87% identical), dog SLC35D2 (85% identical), guinea pig SLC35D2 (84% identical), macaque SLC35D2 (83% identical), tropical clawed frog slc35d2 (59% identical), zebrafish slc35d2 (57% identical), Caenorhabditis elegans sqv-7 (46% identical), Drosophila melanogaster frc (43% identical). Paralogues in human: SLC35D1 (53% identical), SLC35D3 (20% identical), SLC35C1 (18% identical), SLC35E2B (18% identical), SLC35D4 (18% identical), SLC35H1 (18% identical), SLC35E3 (17% identical), SLC35E4 (16% identical), SLC35E1 (15% identical).
Diseases named in the same sentence as SLC35D2 in open-access papers:
SLC35D2 is named in the same sentence as 5 diseases in open-access papers, as found by Europe PMC text mining. Sharing a sentence is not in itself a finding about the gene and the disease. The quoted sentences say what the papers report.
Hydrocephalus (2 papers, 2024 to 2025). Hydrocephalus is an active distension of the ventricular system of the brain resulting from inadequate passage of CSF from its point of production within the cerebral ventricles to its point of absorption into the systemic circulation. "However, none of the three neighboring genes (Hsd17b3, Slc35d2, Zfp367) within 100 kb of BAC/APOL1-G1 insertion site (mm39, chr13: 64,197,419) were plausibly related to hydrocephalus." (PMID 39803526, 2024).
migraine (1 paper, 2023). "It should be noted that patient 5 had variants in one migraine gene, SLC35D2, and two inner ear genes, OTOP1 and LAMA2." (PMID 37107589, 2023). "The majority of the identified variants were found in genes previously associated with migraine (LRP1, ECM1, CARF, CTIF, RNF213, APOE, SLC35D2), with two different rare LRP1 variants each identified in two unrelated children with vertigo." (PMID 37107589, 2023).
infection (1 paper, 2016). The state of being infected such as from the introduction of a foreign agent such as serum, vaccine, antigenic substance or organism. "To test this hypothesis we silenced SLC35D2 expression using siRNA prior to infection." (PMID 26981769, 2016). "We depleted Gys1 and SLC35D2 for 48 hr before infecting the cells, and applied PAS staining 48 hr after infection." (PMID 26981769, 2016).
SLC35D2 also shares sentences with these, for which no sentence is quoted: tumor (1 paper); Vertigo (1).